MMP9 (matrix metallopeptidase 9)
Diseases named in the same sentence as MMP9 in open-access papers (continued):
Sharing a sentence is not in itself a finding about the gene and the disease.
cardiovascular diseases (continued). "Interestingly, the interaction of NGAL with MMP-9 may be a mechanism by which the proteolytic activity of MMP-9 is modulated in the vascular repair process indicating a role for NGAL in cardiovascular disease (CVD)." (PMID 22325322, 2012). "MMP-9 and -12 function in tissue remodeling and may play roles in cardiovascular disease (CVD)." (PMID 21887284, 2011). "The fact that TIMP-1 is the inhibitor also of other MMPs than MMP-9 (notably MMP-1), and these MMPs may also be important in the pathophysiology of cardiovascular disease, may partly explain why TIMP-1 was a stronger marker than MMP-9 of cardiovascular disease risk in this and other studies." (PMID 21283828, 2011). "In cardiovascular disease, sustained hyperactivity of MMP-2 and MMP-9 drives ECM degradation, maladaptive remodeling and ventricular dysfunction." (PMID 41154680, 2025). "The gelatinases, MMP-2 and MMP-9, as well as matrilysin (MMP-7), have been the focus of extensive research in various cardiovascular diseases, largely because of their crucial involvement in the regulation of VSMC migration and proliferation." (PMID 39200884, 2024). "Also, cumulative evidence has suggested that autophagy plays an important role in the pathogenesis of cardiovascular diseases and tumors via the regulation of MMP-2 and MMP-9." (PMID 36211598, 2022). "Saliva has emerged as a non-invasive tool for assessing MMP-9 and MPO in cardiovascular diseases." (PMID 30726210, 2019). "Interestingly, a few studies have indicated that salivary levels of MMP-9 and MPO are potentially promising biomarkers in cardiovascular disease." (PMID 30726210, 2019). "It has been shown that changes in the level of MMP-9, as well as TIMP-1, associated with nonspecific inflammation, and the balance between MMP-9 and TIMP-1 depend on the etiological cause and stage of the cardiovascular disease continuum." (PMID 33224989, 2020). "The investigators suggested that NGAL and MMP-9/NGAL complex levels should be further evaluated in patients with PCOS, because the decreased levels of these atherogenic molecules might protect patients with PCOS against cardiovascular disease (CVD)." (PMID 21143924, 2010). "This hypothesis is supported by previously published results of a randomized controlled trial with non-diabetic patients suffering from cardiovascular diseases and elevated hs-CRP, where a significant beneficial effect of pioglitazone on hs-CRP, MMP-9 and PAI-1 could be demonstrated." (PMID 21756323, 2011).
inflammation (66 papers, 2005 to 2026). Aberrant reaction of the microcirculation characterized by movement of fluid and leukocytes from the blood into extravascular tissues. "Despite the fact that both CXCL8 and MMP-9 are important factors associated with neutrophilic airway inflammation, there are few therapeutic agents for these factors involved in neutrophilic airway inflammation." (PMID 32823491, 2020). "Up-regulation of matrix metalloproteinase-9 (MMP-9), a type IV collagenase, associated with antenatal lung inflammation, may play an important role in the pathogenesis of BPD." (PMID 39795932, 2024). "MMP-9 is a proteolytic enzyme that plays a crucial role in tissue remodeling and has been found to be involved in the development of airway inflammation." (PMID 39796284, 2025). "Lung inflammation induces the formation of neutrophil extracellular traps (NETs), which concentrate neutrophil elastase and matrix metalloproteinase 9 (MMP9) at laminin." (PMID 39682769, 2024). "In alipopolysaccharide-induced acute lung inflammation in BALB/C mice, intraperitoneal eucalyptol attenuated the inflammation-associatedincreases in MMP-9 expression indicating an anti-inflammatory effect." (PMID 37886137, 2023). "Research has shown that fecal MMP-9 concentration reflects the activity of bowel inflammation and mucosal healing in UC." (PMID 33800267, 2021). "Within the MMP family, MMP-9 is suspected to play a predominant role in several murine models of acute lung injury but also in patients with acute lung inflammation." (PMID 25313925, 2014). "In conclusion, our results suggest that NGF exacerbated the effects of OVA sensitization (airway inflammation, remodeling and hyperresponsiveness) via Th2 and MMP-9 pathways." (PMID 24223654, 2013). "Downregulation of MMP-9 activity was demonstrated in lung inflammation in an in vivo murine model and in in-vivo-like bone tissue cultures with active osteoclasts." (PMID 23139770, 2012). "In mice, airway inflammation induced by LPS is associated with an increase of the matrix metalloproteinases (MMP), MMP-2 and MMP-9." (PMID 16091136, 2005). "In addition, it was recently shown that in presence of low levels of pulp inflammation (evaluated by MMP-9 quantification), the irrigant (saline vs. 2.5% NaOCl) had little impact on the direct pulp capping outcome." (PMID 35160239, 2022). "In addition to a-Sma, matrix metalloproteinases such as Mmp9 and Timp1 are also involved in the development and progression of liver inflammation and fibrosis." (PMID 31921324, 2020). "Many reports have shown that excessive expression of MMP-9 could lead to brain inflammation and breakdown of BBB in the traumatic, hemorrhagic and ischemic brain injury." (PMID 28769771, 2017). "Interestingly, airway levels of IL-8, NE, MMP-9, TLR2 mRNA and neutrophils were highly correlated, indicating that these mediators are both associated with neutrophilic airway inflammation and each other." (PMID 21483784, 2011). "The significance of MMP-9 in the airways needs further investigations, since it has also been suggested that MMP-9 may have protective role at least against ozone induced airway inflammation." (PMID 20226090, 2010). "Further, this accumulation of B cells correlated with acute brain inflammation measured by MRI and with inflammatory CSF parameters such as the number of CSF leukocytes, intrathecal IgM and IgG synthesis and intrathecal detection of MMP-9 and CxCL-13." (PMID 18596942, 2008). "Matrix Metalloproteinase 9 (MMP9), a candidate molecular biomarker of serious pulpal inflammation, and inflammatory cell infiltration were observed in the same area." (PMID 41906324, 2026). "Circulating markers such as IL-6, myeloperoxidase (MPO), MMP-9, hsCRP, CD47, and LDL cholesterol have demonstrated utility in characterizing chronic vascular inflammation." (PMID 41007845, 2025).
inflammation (continued). "Taken together, our data show that PYC administration effectively inhibited ASD-induced pulmonary inflammation and suppressed MMP-9 expression, highlighting PYC as a potential therapeutic agent for treating ASD-driven pulmonary inflammation." (PMID 38465002, 2024). "Considering MMP-9’s implication in various brain disorders, we explored RNT’s potential neuroprotective effects against brain inflammation by targeting oxidative stress and MMPs." (PMID 38137419, 2023). "MMP9 and MMP13 expressions are also elevated in cartilage pathologies as well as in synovial inflammation and have been discussed as biomarkers for OA." (PMID 36627721, 2023). "CIE alleviated OVA-induced airway inflammation by restraining phosphorylation of NF-κB and the sequentially reduced expression of iNOS, COX-2, leading to reduced MMP-9 expression." (PMID 35631208, 2022). "Subsequently, the expression of molecules crucial for the development of vascular inflammation, including IL-6, MMP-2, MMP-9, VCAM-1, and ICAM-1, was measured." (PMID 34336088, 2021). "CEACAM1 correlated with vascular inflammation in the aorta, and CEACAM1, MMP9, MPO, ERV3-1, UBALD2 and LSMEM1 correlated with vascular inflammation in the carotid arteries." (PMID 34639156, 2021). "Moreover, melatonin could effectively reduce brain inflammation by inhibiting nuclear factor kappa B (NF-κB) translocation and matrix metallopeptidase-9 (MMP-9) activation in lipopolysaccharide (LPS)-induced inflammation in both in vivo and in vitro experimental models." (PMID 33102250, 2020). "In fact, previous studies reported that the absence or knockdown of PAI-1 decreased eosinophilic airway inflammation, AHR, and airway remodeling in the murine model of acute asthma by inducing fibrinolytic responses through plasmin and MMP-9 activations." (PMID 25785861, 2015). "The soluble MMP-9-cleaved ectodomain of NINJ1 (sNINJ1) exerts anti-inflammatory and atheroprotective effects, creating a functional paradox in which a single protein can both promote and restrain cardiovascular inflammation." (PMID 41841425, 2026). "Although MMP-9 is ubiquitously expressed by a variety of cell types, neutrophils contain substantial amounts of MMP-9 and constitute the primary source in neutrophilic airway inflammation." (PMID 36362203, 2022). "The ELA group exhibited increases in alveolar neutrophil infiltration, the numbers of TNF-α, MAC-2, MMP-9, MMP-12, TIMP-1, eNOS, and iNOS-positive cells and the volume fraction of the 8-iso-PGF2 α, suggesting the presence of lung inflammation, remodeling, and oxidative stress processes." (PMID 27528793, 2016). "The findings suggest that BK-induced MMP-9 expression and cell migration may contribute to increase BBB permeability and recruit immune cells, leading to brain inflammation and edema." (PMID 23176293, 2012). "Our results showed that NGF significantly increased eosinophilic airway inflammation, persistent airway hyperresponsiveness (AHR), the serum levels of OVA-specific IgE and the levels of Th2 cytokines in the BAL fluid, and also increased the expression levels and activity of MMP-9." (PMID 24223654, 2013). "The close relationship of MMP-9 with WBC count in smoking status provides an explanation for the overlap of these two biomarkers for those diseases; 3) As MMP-9 is an emerging biomarker for many inflammation-related diseases, caution should be exercised that WBC count can be a confounding factor." (PMID 23825535, 2013).
neurological diseases (55 papers, 2012 to 2025). "This article discusses a relationship between development of the nervous system diseases and the functional single nucleotide polymorphism (SNP) at position -1562C/T within the MMP-9 gene." (PMID 37206663, 2023). "The polymorphisms of the MMP-9 gene have been implicated in the development of neurological disorders." (PMID 32460746, 2020). "While MMP-9 activity is important for normal CNS development and for the consolidation of long-term memories from development through adulthood, misregulated expression and/or activity of MMP-9 is associated with many neurological disorders." (PMID 26283917, 2015). "Notably, S100A8/A9 and MMP-9 have also been implicated in neuroinflammatory processes in other neurological disorders characterized by CI, such as AD and MS." (PMID 38332909, 2023). "Therefore, it is not surprising that many publications were analyzing the existence of a relationship between MMP-9-1562C/T polymorphism and neurological disorders." (PMID 37206663, 2023). "In this review, we highlight the current evidence for PNN abnormalities in CNS disorders associated with altered network function and MMP-9 levels, emphasizing the need for future work targeting PNNs in pathophysiology and therapeutic treatment of neurological disorders." (PMID 30123106, 2018). "MMP2 and MMP9 which have numerous substrates play important roles in the nervous system during development and in the adulthood as well as after injury and have been implicated in neurological disorders and diseases." (PMID 28819302, 2017). "MMP9 plays a critical role in the pathological progression of various nervous system disorders, including the disruption of the blood–brain barrier, promotion of neuroinflammation, and activation of microglia." (PMID 40224222, 2025). "As a member of the matrix metalloenzyme family, the MMP9 protein is involved in the pathological process of a variety of nervous system diseases." (PMID 40224222, 2025). "MMP9 is important for mediating neuroinflammation and participates in several neurological diseases including neuropathic pain." (PMID 37304762, 2023). "A comprehensive investigation was conducted to examine the function of MMP-9 in the etiology of various neurological diseases." (PMID 37874393, 2023). "At present, little is known regarding the effect of kaempferol and wogonin on MMP-9 in neurological diseases model." (PMID 37270490, 2023). "For example, MMP9, also known as gelatinase B, was found to be an important factor in the occurrence of cardiovascular and nervous system diseases." (PMID 36034287, 2022). "Elevated MMP9 levels are apparent in a variety of neurological disorders where they have been shown to perpetuate disease progression." (PMID 34034683, 2021). "MMP9 levels in the brain are elevated in a variety of neurological disorders, including AD, and contribute to disease formation and progression." (PMID 34034683, 2021). "MMP-9 belongs to the extracellular protease family, which is normally expressed at low levels, but overexpressed in many neurological diseases." (PMID 34685627, 2021). "Darlix and colleagues also reported on serum biomarkers, originally found to reflect central nervous system damage in neurological diseases (NSE and MMP-9), to also significantly associate with BCBM progression following multivariate analysis." (PMID 32110283, 2020). "Increased levels of TNF-α in the blood activates matrix metalloproteinase 9 (MMP-9), which causes blood-brain barrier (BBB) disruptions and induces related neurological disorders." (PMID 31991572, 2020). "The tetracycline drug minocycline, proposed for the treatment of various types of neurological diseases, happens to be an inhibitor of MMP-9." (PMID 22970361, 2012). "The ability of tetracyclines to inhibit MMPs constitutes the basis for their use in treating periodontitis (doxycycline) and in animal models of neurological diseases (minocycline, a neuroprotective MMP-9 inhibitor)." (PMID 22970361, 2012).
neurological diseases (continued). "Moreover, MMP-9 has been shown to be involved in neuroinflammation and various neurological disorders." (PMID 38922117, 2024). "While AXIN, uPA, OSM and MMP9 may be emerging as potential biomarker targets, their performance and specificity is not yet well understood across multiple populations and neurological diseases." (PMID 35734478, 2022). "While therapeutic strategies targeting MMP9 could improve some aspects of neurobehavioral dysfunction in AD, additional studies are needed to better understand the role of MMP9 in neurological disease." (PMID 34034683, 2021). "In addition, MMP-9 is upregulated in a number of neurologic diseases, which can be mediated by TLR4." (PMID 33487119, 2021). "Furthermore, MMP-9 has been shown to mediate increased BBB permeability in neurologic diseases, including during WNV infection and VEEV infection of mice." (PMID 33487119, 2021). "Convincing evidence suggested that the MMP-9 protein could contribute to the onset of neurological disorders, confirmed by serum MMP-9 level that was significantly higher in schizophrenic patients." (PMID 32460746, 2020). "For example, MMP-9 contributes to excitotoxicity-mediated pathogenesis and neurological disorders." (PMID 29742163, 2018). "Matrix metalloproteinase-9 (MMP-9 or gelatinase B) expression is elevated in neurological diseases and its activation is an important factor in detrimental outcomes including excitotoxicity, mitochondrial dysfunction and apoptosis, and increases in inflammatory responses and astrogliosis." (PMID 24194849, 2013). "We use matrix metalloproteinase-9 (MMP-9) as an example of an ECM modifier that has recently emerged as a key molecule in regulating the morphology and dysmorphology of dendritic spines that underlie synaptic plasticity and neurological disorders, respectively." (PMID 25071472, 2014). "MMP-9 and MMP-2 are expressed in the brain, spinal cord, and DRG, and are often increased in response to inflammation, injury, or neurological diseases." (PMID 34631222, 2021). "Therefore, MMP-9 may be a therapeutic target in inflammation-mediated neurological diseases." (PMID 30669368, 2019). "MMP-9 has been shown to degrade components of the basal lamina, leading to disruption of the BBB, and to contribute to neuroinflammatory responses in many neurological diseases." (PMID 22251375, 2012). "Also, data on the varicella zoster virus (VZV) neurologic disease in humans suggest involvement of multiple MMPs, with an increased concentration of MMP2 and to a lesser degree of MMP3 and MMP9 both in serum and CSF, as well as of MMP8 and MMP12 in CSF only." (PMID 40003967, 2025). "The current study seeks to further define MMP-2 and MMP-9 protein levels and enzyme activity in the serum and CSF of ALS and compare their levels to those in the serum of age-matched, healthy controls (HCs) and CSF of other neurological diseases (OND)." (PMID 41009467, 2025). "Matrix metalloproteinase-9 (MMP-9) belongs to the matrix metalloproteinase (MMP) family of zinc-containing endopeptidases and was identified to be involved in the pathophysiology of various neurological diseases, including SAH." (PMID 36339041, 2022). "Despite its implications in AD and other neurological disorders, MMP9 has not been formally investigated as a target in AD models." (PMID 34034683, 2021). "As MMP-9 cleaves PNN components, perhaps the use of more specific MMP-9 inhibitors may yield higher efficacy in treatment of these and other neurological disorders." (PMID 30123106, 2018). "Understanding how other MMP-9 and PNN modifying enzymes are regulated may contribute to the development of new targets in treating neurological disorders." (PMID 30123106, 2018). "A human study measuring MMP-9 levels in the CSF and serum of controls and patients with various neurological disorders showed that MMP-9 was not expressed in the CSF of controls but was markedly increased in the CSF of patients." (PMID 26973468, 2016).
neurological diseases (continued). "Matrix metalloproteinase (MMP)-9 has been shown to degrade components of the basal lamina, leading to disruption of the blood-brain barrier (BBB) and to contribute to neuroinflammatory responses in many neurological diseases." (PMID 22251375, 2012). "For MMP-9, there were studies describing either a positive or a non-linear correlation of protein levels, CSF cell count and blood–brain-barrier impairment in various neurological diseases." (PMID 28806983, 2017). "Moreover, CSF levels of MMP-9 were reduced after 12 months of Natalizumab treatment in 7 MS patients and in the same study CSF MMP-9 mean levels were higher in MS patients before Natalizumab treatment than in patients with other neurological diseases." (PMID 27340316, 2016). "From our results it is clear that the levels of total MMP-9 are not specific to ALS and that other neurological diseases are undergoing processes that are generating similar MMP-9 levels." (PMID 41009467, 2025).